USP14 (ubiquitin specific peptidase 14)
Diseases named in the same sentence as USP14 in open-access papers (continued):
Sharing a sentence is not in itself a finding about the gene and the disease.
prostate carcinoma (20 papers, 2017 to 2024). A carcinoma that arises from epithelial cells of the prostate gland. "In autophagy-deficient prostate cancer cells, USP14 acts as a regulator of DNA damage response by negatively regulating RNF168-dependent ubiquitination signaling and disrupting DNA damage response signaling in autophagy-deficient cells." (PMID 38819674, 2024). "The current study has discovered that USP14, one of the 19S proteasome-associated DUBs, is involved in the stabilization of AR proteins and promotes G0/G1 to S phase transition in human prostate cancer cells and also identified USP14 as a potential target for prostate cancer therapy." (PMID 28151478, 2017). "USP14 is elevated in prostate cancer and AR-positive BCa, and the expression of USP14 is positively correlated with that of AR." (PMID 36423684, 2022). "USP14 is often overexpressed in tumours and has been shown to deubiquitinate and stabilise the androgen receptor in models of breast and prostate cancer." (PMID 36240066, 2022). "For example, USP14 interacts with androgen receptor (AR) to regulate the progression in prostate cancer and breast cancer." (PMID 33771975, 2021). "We performed a cell proliferation assay under two conditions: First, we transfected human prostate cancer cell lines LNCaP cells with siRNAs targeting FASN or USP14, either individually or together." (PMID 34948233, 2021). "A recent study revealed the enhancement of ubiquitination and the degradation of the androgen receptor (AR) in prostate cancer as a result of inhibiting USP14." (PMID 31013812, 2019). "In summary, via demonstrating the role of USP14 in AR stabilization in androgen-responsive prostate cancer, here we provide a potentially new strategy for inhibiting AR-mediated prostate cancer carcinogenesis or progression through inhibition of USP14." (PMID 28151478, 2017). "We have previously reported that USP14 regulates prostate cancer proliferation by deubiquitinating and stabilizing androgen receptor." (PMID 28968984, 2017). "In the current study, we have identified ubiquitin-specific protease 14 (USP14) as a novel regulator of AR, inhibiting the degradation of AR via deubiquitinating this oncoprotein in the androgen-responsive prostate cancer cells." (PMID 28151478, 2017). "First we observed that USP14 was expressed in both androgen-responsive prostate cancer LNcap cells and androgen-irresponsive prostate cancer DU145 and PC3 cells." (PMID 28151478, 2017). "We then sought to address why USP14, which is expressed in both androgen-responsive and -irresponsive prostate cancer cells, plays a starkly different role between the two types of prostate cancer cells." (PMID 28151478, 2017). "Our recent study showing that IU1 significantly decreased the growth of androgen-responsive prostate cancer cells through induction of ubiquitination and degradation of androgen receptor highlights the therapeutic role of USP14 inhibitors." (PMID 29039082, 2017). "Downregulation of USP14 may suppress cell proliferation, migration, and promote cell apoptosis via stabilizing AR in prostate cancer or AR-positive BCa." (PMID 36423684, 2022). "In prostate cancer, USP14, USP22, and USP26 were reported to play roles in cancer progression." (PMID 34545063, 2021). "Inhibition of USP14 may be a highly effective therapy for prostate cancer through degrading AR protein." (PMID 29039082, 2017). "Furthermore, changes in key cell cycle regulators induced by the manipulation of USP14 function also support the notion that AR is a key target for USP14 in the prostate cancer cells." (PMID 28151478, 2017). "Hence, we conclude that USP14 promotes prostate cancer progression likely through stabilization of AR, suggesting that USP14 could be a promising therapeutic target for prostate cancer." (PMID 28151478, 2017).
prostate carcinoma (continued). "Relationships between transcription factors and DUBs can be complex: for example USP7, USP12, USP14, USP22 all appear to regulate the stability and function of androgen receptor (AR) in prostate cancer." (PMID 30854565, 2019). "Similarly, we treated androgen-irresponsive prostate cancer DU145 and PC3 cells with various concentrations of IU1 or with USP14 siRNA, followed by the MTS assay." (PMID 28151478, 2017). "Our study shows that inhibiting USP14 expression or its function leads to cell proliferation inhibition and cell cycle arrest at the G0/G1 phase in androgen-responsive prostate cancer cells but not in androgen-irresponsive prostate cancer cells." (PMID 28151478, 2017). "Our gene expression analyses of androgen-responsive prostate cancer cells exposed to IU1 or USP14 siRNA show a downregulation of PSA but not AR mRNA expression, suggesting that USP14 might not enhance the transcriptional activity of AR." (PMID 28151478, 2017). "To determine the basic role of USP14 in prostate cancer, we used the CellTiter 96 Aqueous One Solution reagent (MTS) assay to test the effect of various concentrations of IU1 (6.25, 12.5, 25, 50, 100 μM), a selective and potent inhibitor of USP14, on the cell growth of LNcap cells." (PMID 28151478, 2017).
hepatocellular carcinoma (19 papers, 2016 to 2025). A malignant tumor that arises from hepatocytes. "Our findings revealed that the overexpression of HK2 partially counteracted the inhibitory effects of USP14 on various biological functions of hepatocellular carcinoma cells, including proliferation, invasion, migration, glycolysis, and apoptosis promotion." (PMID 38383348, 2024). "Our extensive analysis revealed that the activities of hepatoma cells, including proliferation, invasion, migration, apoptosis, glycolysis, and autophagy, were significantly affected by USP14 through its interaction with HK2." (PMID 38383348, 2024). "The deubiquitination activity of USP14 induces proliferation, invasion, migration, and vascular mimicry of hepatocellular carcinoma via maintenance of HIF1-α stability." (PMID 37046655, 2023). "Excitingly, we revealed a novel mechanism by which hepatocellular carcinoma tissues tolerate hypoxic adversities and maintain sustained malignant biological behavior through the modulation function of USP14 on HIF1-α-mediated transactivation." (PMID 34420039, 2021). "USP14 also plays important roles in tumor death, for example, USP14 inhibits hepatocellular carcinoma apoptosis by stabilizing the GPX4 protein, and the inhibition of USP14 increases the degree of gastric cancer apoptosis, with an increased expression of cleaved caspase-3 and cleaved PARP." (PMID 37686660, 2023). "Ubiquitin-specific proteinase 14 (USP14) regulates inflammation, hepatocellular carcinoma and viral infection, but the effect of USP14 on NAFLD is unknown." (PMID 37633951, 2023). "When hepatocellular carcinoma occurs, the USP14 protein level is abnormally increased in HCC tissues." (PMID 34420039, 2021). "Similarly, USP14 maintains HIF-1α stabilization via its deubiquitination activity in hepatocellular carcinoma (HCC)." (PMID 39757165, 2025). "The USP family is the most versatile and powerful deubiquitinating enzyme that has been studied, and USP14, which belongs to the USP family, is widely involved in different signaling pathways mediating proliferation and metastasis in hepatocellular carcinoma." (PMID 37633951, 2023). "Moreover, it has reported that USP14 and USP8 contribute to HIF-1α stabilization in ciliogenesis and hepatocellular carcinoma, respectively." (PMID 39757165, 2025). "Furthermore, we observed that the overexpression of HK2 partially attenuated the inhibitory effect of USP14 on the AKT and P62 signaling pathways in hepatoma cells." (PMID 38383348, 2024). "In hepatocellular carcinoma, USP14 was found highly expressed in HCC tissues and was a negative prognostic biomarker in HCC." (PMID 36582601, 2022).
multiple myeloma (17 papers, 2015 to 2024). "Our findings demonstrate promising antiproliferative activity of VLX1570 in multiple myeloma, primarily associated with inhibition of USP14 activity." (PMID 27264969, 2016). "USP14 influences the incidence of breast cancer, lung adenocarcinoma, multiple myeloma, and other types of tumors." (PMID 37035133, 2023). "USP14 inhibits apoptosis by inhibiting the bcl‐XL signaling pathway and promotes proliferation by stimulating the Wnt signaling pathway in multiple myeloma." (PMID 37035133, 2023). "USP14 was involved in cell adhesion-mediated drug resistance in multiple myeloma by acting as a bridge between Bcl-xl apoptosis pathway and Wnt signaling pathway." (PMID 37082728, 2023). "Similar high USP14 expression levels were observed in epithelial ovarian cancer, multiple myeloma, intrahepatic cholangiocarcinoma, and other tumors." (PMID 37035133, 2023). "Previous studies have suggested that USP14 is a potential target for anti-tumor therapies as shown in cancer cell models of multiple myeloma, lymphomas, breast, lung, liver, and colon cancer." (PMID 37711852, 2023). "USP14 inhibitor VLX1570 was the first DUB inhibitor to enter clinical trials for multiple myeloma therapy, but was deferred due to pulmonary toxicity." (PMID 34483932, 2021). "P5091 (inhibitor of USP7) and b-AP15 (inhibitor of USP14/UCHL5) inhibit the growth of bortezomib-resistant multiple myeloma [41,42,]." (PMID 34272356, 2021). "Concurrent pharmacological inhibition of the proteasome-associated DUBs USP14 and UCHL5 reduces proliferation, and increases survival in multiple myeloma xenograft models." (PMID 29474458, 2018). "Transient knockdown of USP14 or UCHL5 expression by electroporation of siRNA reduced the viability of multiple myeloma cells." (PMID 27264969, 2016). "Exposure of multiple myeloma cells to VLX1570 resulted in thermostabilization of USP14 at therapeutically relevant concentrations." (PMID 27264969, 2016). "The importance of deubiquitinating enzymes in myeloma pathogenenesis, and their potential as drug targets, was recently demonstrated using an inhibitor targeting USP7, and another targeting UCH-L5 and USP14, two proteasome-associated DUBs." (PMID 26513019, 2015). "In addition, a study has shown that USP14 could down-regulate cyclins and activate aspartic proteases-dependent apoptotic pathways, thereby blocking the growth of myeloma cells." (PMID 37082728, 2023). "This is achieved by inhibiting the enzymatic activity of USP14 and UCHL5, and VLX1570 shows significant anti‐cancer impact in multiple myeloma and Waldenstrom's macroglobulinemia." (PMID 34854221, 2022). "In 2015, as a competitive inhibitor of proteasomal DUBs (preferring USP14 over UCHL5), VLX1570 became the first case applied in phase I trials for treating multiple myeloma and solid tumors, although it has been discontinued because of dose-limiting toxicity." (PMID 35883466, 2022). "We next used an siRNA approach to knock down the expression of USP14 and UCHL5 in multiple myeloma (MM) cells." (PMID 27264969, 2016). "We show that USP14 is the preferential target of VLX1570 and suggest that the high expression of USP14 in multiple myeloma cells confers increased sensitivity to proteasome DUB inhibition with VLX1570." (PMID 27264969, 2016). "Combined inhibition of USP14 and the proteasomal DUB ubiquitin C-terminal hydrolase 37 (UCH37) in multiple myeloma cells delays proteasome-mediated protein degradation, halts the cell cycle, and leads to tumor cell apoptosis." (PMID 25575639, 2015). "VLX1570 targets the Ub‐USP14 or Ub‐UCHL5 conjugates and is a reversible non‐selective competitive inhibitor of ubiquitin peptidase 14 (USP14) and ubiquitin carboxyl‐terminal hydrolase 5 (UCHL5) in multiple myeloma." (PMID 34854221, 2022).
multiple myeloma (continued). "For example, combined inhibition of USP14 and the proteasomal deubiquitinating enzyme UCH37 halts protein degradation and promotes apoptosis in multiple myeloma cells, whereas USP14 inhibition alone accelerates the degradation of aggregate-prone proteins in immortalized cell lines." (PMID 25575639, 2015).
gastric cancer (15 papers, 2017 to 2025). A primary or metastatic malignant neoplasm involving the stomach. "USP14 was found to be associated with poor tumor prognosis and an unfavorable immune phenotype in gastric cancer patients and mouse tumor models." (PMID 39944823, 2025). "Knockdown of USP14 triggers cisplatin induced apoptosis by blocking the Akt and ERK signalling pathways, thereby rendering gastric cancer cells more susceptible to cisplatin." (PMID 39928282, 2025). "High USP14 levels in stomach cancer have emerged as a potential prognostic marker for patient survival without disease recurrence." (PMID 39605891, 2024). "YTHDF1 has been demonstrated to promote the metastasis of gastric cancer in an m6A-dependent way by promoting USP14 translation." (PMID 38042806, 2023). "USP14, a member of the ubiquitin-specific proteases (USP) family, has been linked to the progression of various cancers, including colorectal, pancreatic, breast, and gastric cancers." (PMID 40316942, 2025). "IU1 was able to reverse resistance to 5-FU in gastric cancer cells by inhibiting USP14 activity." (PMID 39605891, 2024). "Previous studies have reported that YTHDF1 promotes the occurrence and metastasis of gastric cancer in an m6A-dependent manner by promoting the translation of USP14 and it may represent a potential target for gastric cancer treatment." (PMID 34677810, 2021). "The depletion of USP14 sensitizes gastric cancer cells to cisplatin-induced cell death." (PMID 33919439, 2021). "For example, the downregulation of miR-320a increases the stability of vimentin in gastric cancer (GC) cells by enhancing USP14, thus upregulating vimentin and promoting GC cell growth, migration, and invasion." (PMID 37917013, 2023). "Conversely, the administration of IU1 (a USP14 inhibitor) effectively suppresses FAO-induced M2 polarization and tumor growth in gastric cancer (GC)." (PMID 38715050, 2024). "The activation of USP14 determines the increased stability of the SIRT1 protein and is essential for the activation of fatty acid oxidation and the immunosuppressive phenotype in macrophages derived from gastric cancer." (PMID 39944823, 2025).
ovarian carcinoma (14 papers, 2016 to 2025). A malignant neoplasm originating from the surface ovarian epithelium. "Very importantly, mutations to Ser in USP14 occurred in skin cutaneous melanoma, uterine endometrioid carcinoma, prostate adenocarcinoma, and ovarian cancer." (PMID 38247539, 2024). "Previous studies have shown that USP14 profiles are implicated in ovarian cancer, lung adenocarcinoma, non-small cell lung cancer and neuroblastoma." (PMID 37917013, 2023). "Aberrant expression of USP14 has been implicated in a variety of cancers, including multiple myeloma, colorectal cancer, lung cancer, and epithelial ovarian cancer." (PMID 27121063, 2016). "Notably, aberrant expression of USP14 in epithelial ovarian cancer has been associated with poor prognosis." (PMID 27121063, 2016). "For example, USP14 promotes resistance to cisplatin of ovarian cancer by increasing the stability of BCL6 protein." (PMID 39928282, 2025). "Inhibition of USP14 promoted connexin 32 internalization and counteracted cisplatin cytotoxicity in human ovarian cancer cells." (PMID 37082728, 2023). "bAP15, an inhibitor of the 19S proteasome DUBs UCHL5 and USP14, results in cell growth inhibition in several human cancers; however, the mechanism remains poorly understood in ovarian cancer." (PMID 31666925, 2019). "As a potential drug target for the failure of chemotherapy, Connexin 32 internalization by USP14 inhibition modulates cisplatin resistance in ovarian cancer cells; however, little attention has been paid to the role of GJB3 in cancer, especially from a pan-cancer perspective." (PMID 38728250, 2024). "USP14 has increased expression in cisplatin‐resistant ovarian cancer cells." (PMID 37143582, 2023). "USP14 expression is upregulated in several cancers including lung adenocarcinoma, ovarian cancers, esophageal squamous cell carcinoma, and pancreatic ductal adenocarcinoma, in which this enzyme is often positively correlated with tumor recurrence, metastasis, and poor patient survival." (PMID 34207520, 2021). "In addition, we also used the pharmacological USP14 inhibitor IU1 to investigate the effect on cell growth in ovarian cancer cells." (PMID 31666925, 2019). "Other studies have found that USP14 stabilises BACH1 by deubiquitination, regulating heme metabolism through the NRF2 signalling pathway and promoting cancer cell invasion in ovarian cancer." (PMID 40988122, 2025). "A role for USP14 in regulation of cell proliferation and apoptosis has been reported in ovarian carcinoma cells with intrinsic resistance to cisplatin (i.e., SKOV3) in which the expression of USP14 has been shown to be cell-cycle dependent with an increase after serum addition in starved cells." (PMID 39430244, 2024). "However, IU1 did not significantly affect cell growth in the present study, which suggested that USP14 is not critical in ovarian cancer and implied the lack of USP14-mediated androgen receptor signaling in ovarian cancer progression." (PMID 31666925, 2019). "Furthermore, pharmacological inhibition of USP14 with the FDA approved small-molecule inhibitor VLX1570 has been suggested as an alternative treatment method for cancer in a number of cancer settings, including breast and ovarian cancer." (PMID 27121063, 2016).